TOB1 (transducer of ERBB2, 1)
Diseases named in the same sentence as TOB1 in open-access papers (continued):
Sharing a sentence is not in itself a finding about the gene and the disease.
tumor (continued). "Previous data suggests TOB1 is a tumor suppressor that inhibits cancer cell proliferation through various signaling pathways." (PMID 29088861, 2017). "Tumor cell growth was reduced in cells with TOB1 concentrated in the nuclei compared to control cells, in both MTS and colony formation assays." (PMID 29088861, 2017). "Our data indicated that high levels of p-TOB1 in the nuclei of tumor cells were correlated with poor survival in intestinal type GC patients." (PMID 29088861, 2017). "In 34 studies, TOB1 was ranked within the top 10% of all genes showing significant statistical differences, 26 of which revealed lower expression levels in tumor than normal tissues, while eight analyses indicated an opposite result." (PMID 28922388, 2017). "To examine the role of the ERBB3-regulating miR-200c target genes in tumour growth, we generated EGFR-mutated H1975 cell transfectants that stably express short hairpin RNAs against TOB1." (PMID 27456471, 2016). "This review addresses the molecular basis of TOB1 tumor suppressor function with special emphasis on its regulation of intracellular signaling pathways." (PMID 26694352, 2015). "TOB1 tumor suppressor function has been largely confirmed by its anti-proliferative and apoptosis-inducing effects on various cancer cells." (PMID 26694352, 2015). "According to this study, TOB1 interacted with another tumor suppressor protein, SMAD4, and enhanced the binding of SMAD4 to the SMAD binding element (SBE) located on the promoter region of IL-2, thereby dampening IL-2 transcription." (PMID 26694352, 2015). "Altogether, research work from different laboratories using distinct experimental systems undoubtedly proved that TOB1 is a tumor suppressor which negatively regulates the cell cycle and has a significant anti-proliferative activity." (PMID 26694352, 2015). "The tumor suppressor function of Tob1 has largely been corroborated to its anti-proliferative effect on various cancer cells." (PMID 22710759, 2012). "Interestingly, it has been also reported that Tob1 participates in tumor occurrence as well as T-cell activation." (PMID 40918450, 2025). "Although TOB1 has been reported to play an important regulatory role in tumor cell proliferation and apoptosis, its role in host antiviral response remains unclear." (PMID 38512977, 2024). "This prompted us to investigate whether TOB1 played a crucial role in augmenting their anti-tumor functions." (PMID 38617839, 2024). "Relevant literature indicates that TOB1 has a tumor-suppressive effect in various cancer types." (PMID 38617839, 2024). "TOB1 is a member of a family of anti-proliferative factors that act as tumor suppressors." (PMID 35154457, 2022). "In addition, TOB1 is regarded as a tumor suppressor in GC, attenuating the malignant phenotype of GC cells and inhibiting cell cycle progression and proliferation activity." (PMID 35154457, 2022). "Accumulating evidence has shown that TOB1 functions as a tumor suppressor." (PMID 31891232, 2020). "Considering the tumor suppressor function of TOB1 and the fact that the expression of this protein is reduced during carcinogenesis, it is plausible to consider the development of small molecule inducers of TOB1 as anticancer therapies." (PMID 26694352, 2015). "In addition, Tob1, which is ubiquitously expressed in human adult tissues, could work as a tumor suppressor in certain types of cancers." (PMID 40918450, 2025). "Therefore, we have reason to speculate that TOB1 enhanced patient prognosis by enhancing polarizing of neutrophils toward to anti-tumor phenotype and inhibiting their apoptosis." (PMID 38617839, 2024). "Moreover, the role of TOB1 in preventing tumor progression has recently been reported." (PMID 26694352, 2015). "Moreover, in the upcoming years, establishing small molecule inducers of TOB1 activity may be considered as a promising choice for developing new anticancer therapies alongside revealing the biochemistry of TOB1 function as a tumor suppressor." (PMID 26694352, 2015).
tumor (continued). "This age-associated tumor phenotype was not seen in any of 12 age-matched WT (Nfatc2+/+, N = 6) or hemizygous (Nfatc2+/−N = 6) littermates, and unlike previous reports, no tumors developed in young or old Tob1 KO mice." (PMID 24945807, 2014). "StromalScore and ImmunoScore were used to analyze the correlation between APRO (TOB1, TOB2, BTG1, BTG2, BTG3 and BTG4) expression and tumor purity and tumor microenvironment characteristics." (PMID 38062199, 2023). "Subsequently, we applied the COX regression model and conducted ROC analysis to identify the final set of tumor-related genes (TRGs), which included CASP4, FYN, TOB1, and CLEC2B." (PMID 37753069, 2023). "Thus, either Tob1 or ASK1 may also be involved in the suppression of tumour growth of GC by RN181." (PMID 30714150, 2019). "Collectively, our data support a model of CNOT7, TOB1, CNOT1, and RNA-binding proteins collectively exerting post-transcriptional control on a metastasis suppressive transcriptional program to drive tumor cell metastasis." (PMID 26807845, 2016). "Others reported that TOB1 restoration inhibits growth factor receptor ERBB2-mediated signaling and attenuates tumor cell survival." (PMID 26694352, 2015). "TOB1 is a tumor-suppressing protein that functions as a negative regulator of the receptor tyrosine-kinase ERBB2." (PMID 38512977, 2024). "TOB1, a member of the BTG/TOB protein family, inhibits tumor cell proliferation." (PMID 29088861, 2017). "It is possible that proliferation was not suppressed in these tumor cells, despite the cytoplasmic localization of TOB1, because TOB1 was phosphorylated by Erk1/2, which is a downstream effector of the ErbB2 receptor." (PMID 29088861, 2017). "The tumor-specific overexpression of TOB1 results in the activation of other tumor suppressor proteins, such as mothers against decapentaplegic homolog 4 (SMAD4) and phosphatase and tensin homolog-10 (PTEN), and blocks tumor progression." (PMID 26694352, 2015). "We found that the knockdown of TOB1 alone moderately (P=0.074) increased xenograft tumour growth, suggesting that these ERBB3-regulating genes may collaboratively regulate tumour growth in vivo." (PMID 27456471, 2016).
cancer (31 papers, 2011 to 2025). A tumor composed of atypical neoplastic, often pleomorphic cells that invade other tissues. "Supporting a causal relationship between loss of expression and disease, gene inactivation of BTG3 and TOB1 is associated with predisposition to cancer in mouse models." (PMID 23236473, 2012). "In agreement with their anti-proliferative activity, loss of expression of BTG2, BTG3, and TOB1 is frequently observed in clinical samples of various cancers, including lung, thyroid and breast tumours." (PMID 23236473, 2012). "Possibly, the Treg immune cells may play a vital role in the TME of CSCs, in which Tob-1 could exhibit close associations with infiltrating Treg cells within several malignant tumors." (PMID 40296902, 2025). "Several studies have shown that Tob1 expression is suppressed in various cancers, including breast, pancreas, thyroid, and stomach cancer." (PMID 39861074, 2024). "Like many other tumor suppressor proteins, down-regulated TOB1 expression has been reported in various cancers, mostly in breast, pancreas, thyroid, and stomach." (PMID 36849756, 2023). "Here, we discuss contradictory reports on the invasiveness of cancer cells in relation to the actions of Tob1, a member of the APRO family, on the basis of understanding the function of MMPs and/or exosomes." (PMID 36230852, 2022). "The WEE2‐AS1/miR‐32‐5p/TOB1 axis can negatively modulate cancer progression in TNBC cells by inhibiting the expression of TOB1, an oncogene." (PMID 34405957, 2021). "DriverPower also called two 3′-UTR driver candidates in total, including TOB1 in pan-cancer and ALB in Liver-HCC." (PMID 32024818, 2020). "Recurrent somatic events were identified in the 3′ UTRs of TOB1 (carcinoma and pan-cancer meta-cohorts), NFKBIZ (lymphomas) and ALB (liver cancer)." (PMID 32025015, 2020). "Originally, Yoshida9 discovered that TOB1 knockout mice spontaneously formed tumors and suggested that the TOB1 gene played an important role in the formation of malignant tumors." (PMID 31891232, 2020). "Reduced TOB1 expression and altered phosphorylation has been observed in various cancers including lung, thyroid, breast, pancreatic, and squamous cell carcinoma of the skin." (PMID 29088861, 2017). "With regard to TOB1, three of 12 analyses revealed significant difference between cancer and normal groups." (PMID 28922388, 2017). "We also found that the migration of cancer cells with TOB1 concentrated in the nuclei was reduced compared to control cells." (PMID 29088861, 2017). "Like many other tumor suppressor proteins, down-regulated TOB1 expression was reported in various cancers, mostly in breast, pancreas, thyroid, and stomach." (PMID 26694352, 2015). "TOB1-overexpressing cancer cells have limited potential of growing as xenograft tumors in nude mice upon subcutaneous implantation." (PMID 26694352, 2015). "TOB1 antagonizes the v-akt murine thymoma viral oncogene (AKT) signaling and induces cancer cell apoptosis by activating BCL2-associated X (BAX) protein and inhibiting the BCL-2 and BCL-XL expressions." (PMID 26694352, 2015). "Subsequent studies demonstrated that the expression of Tob1 is lost in various cancers including those of the breast, pancreas, thyroid and stomach." (PMID 22710759, 2012). "Like many other tumor suppressor proteins, the expression of Tob1 is frequently lost in various cancers." (PMID 22710759, 2012). "BTG1 belongs to the BTG/TOB family of anti-proliferative genes (BTG1-BTG4, TOB1 and TOB2) implicated in several types of cancer." (PMID 22359517, 2012). "Additionally, Tob1 has been uncovered to trigger autophagy to suppress cancer progression by activating the AKT/mTOR pathway." (PMID 40918450, 2025). "Tob1 might also play a fundamental role in keeping cells in a quiescent state, thereby obstructing the cellular proliferation of normal and/or cancer cells." (PMID 37761875, 2023).
cancer (continued). "In addition, Tob1 deficiency appears to lead to the reduced tumorigenesis in DSS-treated cancer, suggesting that Tob1 is an adverse prognostic factor." (PMID 36230852, 2022). "TOB1, a member of the antiproliferative protein B‐cell translocation gene/transducer of the erbB2 family, can act as a tumour suppressor to inhibit cell proliferation, migration and invasion in different types of human cancers." (PMID 34405957, 2021). "As most of the other tumor suppressor proteins, TOB1 is inactivated in many human cancers." (PMID 26694352, 2015). "TOB1 decreases the migration, invasion, and metastatic ability of cancer cells." (PMID 26694352, 2015). "Thus, it may be concluded that TOB1 selectively induces apoptosis in cancer cells, while it protects normal cells from unwanted cell death." (PMID 26694352, 2015). "Homozygous deletion of TOB1 in mice is reported to be responsible for cancer development in the lung, liver, and lymph node, whereas the ectopic overexpression of TOB1 shows anti-proliferation, and a decrease in the migration and invasion abilities on cancer cells." (PMID 26694352, 2015). "The APRO family includes 6 members: Tob1, Tob2, BTG1, BTG2, Abundant in Neuroepithelium Area (ANA), and BTG4, which some members are of significance for the prognosis of cancers." (PMID 40918450, 2025). "A set of genes, including PNRC1, HERPUD1, TP53INP2, Tob1, and SAT1, were downregulated in patients with different cancer types, and their decreased expression was correlated with poorer prognosis and shorter survival time." (PMID 39861074, 2024). "In the present study, we comprehensively analyzed the role of TOB1, TOB2, BTG1, BTG2, BTG3 and BTG4 in cancer from the perspective of bioinformatics." (PMID 38062199, 2023). "We used bioinformatics methods to analyze the characteristics of TOB1, TOB2, BTG1, BTG2, BTG3 and BTG4 in pan-cancer." (PMID 38062199, 2023). "Through a series of bioinformatics analysis, the findings in our study supported the important role of TOB1, TOB2, BTG1, BTG2, BTG3 and BTG4 in pan-cancer and provided a reliable basis for detecting biomarkers of cancer." (PMID 38062199, 2023). "There are contradictory reports on the invasiveness of cancer cells in the exploitation of the BTG1 protein, the other member of the APRO family, as well as those of Tob1 as shown in the introduction." (PMID 36230852, 2022). "TOB1 and its neighbouring gene WFIKKN2 are focally amplified in breast cancer and pan-cancer, suggesting a complex role in cancer." (PMID 32025015, 2020). "Tob1, a Tob/BTG anti-proliferative protein family member, functions as a tumour suppressor in many cancers." (PMID 30447686, 2018). "Consistent with previous studies, our expression analyses showed that the mRNA levels of TOB1 and BTG2 were reduced in most cancers compared to normal tissues." (PMID 28922388, 2017). "Several members including TOB1-2 and BTG2-3, exhibited significant expression differences between cancer and normal tissue groups in defined cancers." (PMID 28922388, 2017). "Altogether, the transcriptional expression levels of TOB1-2 and BTG2 were significantly reduced in most cancers compared with normal tissues, while BTG3 was upregulated in most cancers." (PMID 28922388, 2017). "We observed that the mRNA expression levels of TOB1-2 and BTG2 were decreased in most cancers compared with normal tissues, while BTG3 was upregulated in most cancers." (PMID 28922388, 2017). "BTG1 belongs to the BTG/TOB family of anti-proliferative genes (BTG1-BTG4, TOB1 and TOB2) and expression of their gene products is altered in a variety of different cancers." (PMID 22359517, 2012). "In these ways, APRO family proteins including Tob1, BTG2, and BTG1 have been reported to control/regulate/promote cell proliferation, cell cycle progression, and/or cell differentiation in various types of cancer." (PMID 40918450, 2025).
cancer (continued). "Additionally, terms related to signaling axes that are commonly hijacked by cancer cells, such as terms related to ALK, TROP2, and TOB1, which is a growth-suppressive factor, and EGFR and ERBB (leading genes DAB2IP and PTPRJ) were enriched in both analyses." (PMID 40564222, 2025). "The CTLA4, TOB1, MYC, Notch, Hedgehog, and EMT pathways play a critical role in cancer progression." (PMID 34095215, 2021). "In this study, we also found that TOB1, BTG1 and BTG3 could be a prognostic marker or potential therapeutic target in several cancer types, consistent with previous reports." (PMID 28922388, 2017). "Consistently, Tob1 overexpression could not only increase the expression of PTEN, but also regulate the downstream effectors in the PI3K/PTEN signaling pathway, leading to the suppression of cancer cell proliferation." (PMID 36230852, 2022). "Many BTG proteins such as BTG4, TOB1, TOB2 are aberrantly expressed and serve as negative regulators in tumorigenesis in various cancers." (PMID 24147003, 2013).
infection (4 papers, 2018 to 2024). The state of being infected such as from the introduction of a foreign agent such as serum, vaccine, antigenic substance or organism. "Among the three cell lines, the anti-FMDV infection phenotype of TOB1-knockout in IBRS-2 cells is the most significant, likely due to the high expression of ISGs." (PMID 38512977, 2024). "We quantified the FMDV genome copy numbers in TOB1-knockout and control cells at 6, 12, and 24 hours post-infection (hpi) using absolute quantitative PCR analysis targeting the 3D gene of FMDV." (PMID 38512977, 2024). "After 24 hours of FMDV infection, TOB1-knockout IBRS-2 cells showed lower cytopathic effect (CPE) and no significant changes in cell viability." (PMID 38512977, 2024). "TOB1 interacted with IRF3 following infection with Sendai virus (SeV, an ssRNA virus recognized by RIG-I), vesicular stomatitis virus (VSV, another ssRNA virus recognized by RIG-I), or lipopolysaccharide (LPS; a Toll-like receptor 4 ligand)." (PMID 36085336, 2022). "TOB1-knockout inhibited the infection of FMDV, presumably through the EGFR/ERBB2 signaling pathway." (PMID 38512977, 2024). "At 72 h post-FMDV infection, the replication level and copy numbers of FMDV RNA were lower in TOB1-knockout mice compared to wild-type mice." (PMID 38512977, 2024).
TOB1 also shares sentences with these, for which no sentence is quoted: lung adenocarcinoma (2 papers); amyotrophic lateral sclerosis (1); anemia (1); ankylosing spondylitis (1); breast invasive carcinoma (1); demyelinating disease (1); hepatocellular carcinoma (1); invasive ductal breast carcinoma (1); kidney cancer (1); lung squamous cell carcinoma (1); metastasis (1); papillary carcinoma (1); Parkinson’s (1); pheochromocytoma (1); prostate adenocarcinoma (1); pulmonary fibrosis (1); Salmonella Infections (1); schizophrenia (1); skin squamous cell carcinoma (1); thyroid tumor (1).